HGF (hepatocyte growth factor)
Diseases named in the same sentence as HGF in open-access papers (continued):
Sharing a sentence is not in itself a finding about the gene and the disease.
glioma (continued). "Increased expression of HGF may be a valuable predictor for prognostic evaluation of glioma patients." (PMID 22741575, 2012). "U87MG glioma cells are dependent on the HGF/SF:c-MET signaling axis for in vivo growth." (PMID 22511956, 2012). "Next, we evaluated whether the FFPE assay could be used to detect endogenous levels of HGF/c-MET complexes in glioma cell lines that activate c-MET signaling through the autocrine production of HGF." (PMID 21283737, 2011). "Furthermore, HGF-c-MET activation in glioma cell lines was verified by Surface Protein-Protein Interaction by Crosslinking ELISA (SPPICE) assay in corresponding soluble cell lysates." (PMID 21283737, 2011). "In addition, detection of endogenous levels of HGF/c-MET in glioma cells was consistent between proximity FFPE and SPPICE biochemical assays." (PMID 21283737, 2011). "In addition, it would be worth to further investigate whether HB-EGF and HGF signaling pathways cooperate to promote DSE-mediated glioma malignancy." (PMID 29864158, 2018). "However, the transmigrationinduced by HGF was lower than that obtained with glioma C6 CM." (PMID 23637756, 2013). "Moreover, HGF siRNA transfection enhanced the chemosensitivity of U87MG glioma cells to cisplatin." (PMID 22741575, 2012). "The aim of this study is to evaluate whether tumor-derived HGF acts as a potent predictive factor for tumor recurrence and prognosis for patients with gliomas, and whether HGF indeed affects tumor progression by altering the biological behavior of tumor cells and increasing drug resistance." (PMID 22741575, 2012). "Tumor-associated fibroblasts (CAFs) can secrete growth factors such as hepatocyte growth factor (HGF), platelet-derived growth factor (PDGF), and transforming growth factor-β (TGF-β), which directly stimulate the proliferation and survival of glioma cells." (PMID 40183013, 2025). "The human MET proto-oncogene is present on chromosome 7q31, and HGF is located on chromosome 7q21.1; the evidence was reported that MET plays a crucial role in glioma cell biology functions such as proliferation, growth, migration, invasion, and stemness." (PMID 38201528, 2023). "H19, a hepatocyte growth factor (HGF) -induced lncRNA, has been shown to be highly expressed in a variety of tumors, including gliomas." (PMID 37228500, 2023). "We first examined HGF and MET expression levels and constitutive MET activation in the GL-261, SMA-497, SMA-540 or SMA-560 mouse glioma models." (PMID 36915128, 2023). "We find that the murine glioma cell lines GL-261, SMA-497, SMA-540 and SMA-560 express HGF and its receptor MET and respond to exogenous HGF with MET phosphorylation." (PMID 36915128, 2023). "It has been shown that HGF/MET signaling can promote growth and migration of gliomas cells via up-regulating COX-2 expression and stimulating the release of PGE2." (PMID 35935338, 2022). "In endothelial cells under glioma conditions, HGF (hepatocyte growth factor) induces direct β-catenin phosphorylation at Ser675 by HGF receptor kinase c-Met, leading to the β-catenin nuclear translocation and LEF1-mediated activation of Wnt target genes." (PMID 36010607, 2022). "Similar to human glioma, HGFR, a high-affinity tyrosine kinase receptor for HGF, was the most abundantly increased molecule evaluated in high-grade canine astrocytoma." (PMID 34131649, 2021). "HGF/MET are key determinants of malignancy in brain tumors, and their expression often correlates with the malignancy grade of gliomas." (PMID 33066121, 2020). "Conversely, inhibition of HGF and MET expression leads to a decrease in in vivo tumor formation and growth of experimental gliomas." (PMID 33066121, 2020). "Increased expression of HGF and MET protein correlates with the degree of vascularization and with the malignancy of glial tumors." (PMID 32607415, 2020). "Regarding dysregulation of the HGF/MET signaling pathway, the SPINT2 gene has been extensively studied in gliomas." (PMID 31221203, 2019).
glioma (continued). "Aligned with this concept, recently a combination of erlotinib and HGF scavenging antibody L2G7 was shown to significantly decrease tumor growth and improve the OS in EGFRvIII/cMET+/HGF+/PTEN−/− glioma models compared to single agents." (PMID 31215502, 2019). "In glioma cell lines, genetic inhibition of ERK5 decreases HGF-induced cell migration and invasiveness in vitro and reduces the expression of the mesenchymal marker N-cadherin and CD44, which are associated with glioma invasiveness." (PMID 30901834, 2019). "Further, the protein expression of hepatocyte growth factor (HGF), the ligand for c-MET, was found to positively correlate and be co-expressed with MMP-2 in human glioma." (PMID 28234925, 2017). "While ligands such as EGF, HGF, and PDGF can stimulate glioma invasion, blocking of these signaling pathways by anti-cancer drugs has not been so effective due to signal transduction redundancy in response to these drugs and co-expression of these molecules." (PMID 28166231, 2017). "Since TGF-β2 induces ERK phosphorylation in a U0126-sensitive manner in glioma cells, we next explored a role for ERK in controlling the HGF/c-MET pathway." (PMID 29238047, 2017). "RMPAhigh gliomas were also enriched in the expression of ERBB2, FGFR1 and MET (and its ligand HGF), DDR2 (a receptor for activated collagen fibers), as well as the WNT co-receptors ROR1 and RYK." (PMID 27385209, 2016). "In high-grade gliomas, the frequently occurring oncogenic EGFR mutant EGFRvIII can induce overexpression of both MET and HGF, a process that is balanced by wild-type EGFR activation." (PMID 25862637, 2015). "In the following year, another group reported that deletion of HGF, or of MET, from glioma cells via a ribozyme technique led to growth arrest in nude mice." (PMID 23296269, 2013). "The results from the in vivo experiment thus demonstrate the capacity ofReNcells CX to pass the BBB and reach intracranial gliomas and confirm the overexpression of HGF,VEGF and zonulin/prehaptoglobin-2 in gliomas." (PMID 23637756, 2013). "The HGF/c-MET axis is important in both angiogenesis and cell migration in several tumor types including glioma." (PMID 23484006, 2013). "Since HGF and vascular endothelial growth factor (VEGF) are the primary chemotactic growthfactors produced by gliomas, we nextanalyzed the effect of VEGF on ReNcell CX transmigration." (PMID 23637756, 2013). "Microglial cells recruited by glioma can promote tumor growth, dictated by paracrine loops responsible for glioma initiation and progression (e.g., IL-6, IL-10, TGF-β, prostaglandins, G-CSF, and GM-CSF, and growth factors such as EGF, VEGF, HGF, and SCF)." (PMID 22319429, 2012). "C-Met protooncogene expression is regulated by hypoxia to enhance scatter factor/hepatocyte growth factor (SF/HGF)-induced cell migration and invasion in glioma and trophoblast cells." (PMID 23241400, 2012). "In glioma cells, autocrine activation of c-MET by HGF-c-MET increased basal levels of c-MET phosphorylation at tyrosine (Tyr) 1003." (PMID 21283737, 2011). "There is a lack of accurate knowledge about the effects of PDT on some molecules that are important for the effectiveness of glioma therapy, such as transforming growth factor β (TGF-β), and the information on some of them (e.g., HGF, HDACs, GFAP, and others) is far from sufficient." (PMID 39201395, 2024). "Glioblastomas (GBM), another highly lethal CNS cancer, is characterized by aberrant activation of multiple pathways, including the Hedgehog (HH) or MET (also known as c-MET, receptor tyrosine kinase for Hepatocyte Growth Factor (HGF)) signaling." (PMID 38273337, 2024). "Indeed, irradiation of glioma stem cells has been shown to induce c-MET upregulation, while in vitro studies have shown that pre-treating GBM cells with HGF reduced the cytotoxic effect of DNA damaging agents." (PMID 36034555, 2022).
glioma (continued). "It has been reported that HGF and MET were highly expressed in glioma to promote tumor growth and angiogenesis, which could also boost tumor evolution and malignant progression to HGG by activating AKT and MAPK pathways." (PMID 35677036, 2022). "Furthermore, hepatocyte growth factor (HGF) upregulated chemokine receptor CXCR4 expression via NF-κB activation, leading to glioma cell (U87MG and LN 229) invasion." (PMID 34439380, 2021). "In brain tumors, HGF and MET expression levels correlate with tumor grade in human gliomas." (PMID 33066121, 2020). "Experimentally, EMT in glioma cells is either triggered by hypoxia and consecutive upregulation of the vascular endothelial growth factor (VEGF) or a hypoxia-independent induction via hepatocyte growth factor (HGF)-mediated MET phosphorylation." (PMID 29844871, 2018). "Further, it has been shown that in GBM cells, EGFRvIII transactivates other RTKs, including the hepatocyte growth factor (HGF) receptor (MET) and co-targeting of these RTKs has a potent antitumor efficacy, thus suggesting a potential strategy for treating EGFRvIII-expressing gliomas." (PMID 26461476, 2015). "Because HGF-autocrine activation is the key molecular feature determining responsiveness to MET inhibitors, we asked whether sensitive glioma subcutaneous xenografts are transcriptionally similar to each other and are dissimilar from insensitive glioma models." (PMID 26381735, 2015). "Although the precise factors responsible for a poor prognosis in gliomas have not been identified, this study indicates high expression of HGF in tumor cells may play a critical role in tumor progression and is a valuable predictor for prognosis evaluation in glioma patients." (PMID 22741575, 2012). "In conclusion, we describe a highly active, non-ligand-dependent mutant of MET in 6 % of gliomas, which is not exposed on the cell surface and is predicted to be non-targetable with therapeutic antibodies against MET and/or HGF." (PMID 25862637, 2015). "Exploration of our scRNA-seq dataset with CellChat26 revealed active HGF/MET signaling to occur exclusively between sending, Hgf-expressing macrophages and receiving, Met-expressing MES II cells in Pdgfbret/ret, but not in Pdgfbret/+ glioma tissue." (PMID 41339360, 2025). "With nanoinhibitors as treatments on TMZ-resistant glioma cells, BIP-MPC-NP simultaneously attenuated p-EGFR and p-MET in cells with EGF and HGF incubation or without EGF and HGF incubation, and this attenuation was more significant than that of EBP-MPC-NP or MBP-MPC-NP group." (PMID 32001707, 2020). "Because the levels of vWF, MMP9, VCAM1, angiogenin, and HGF were increased in both GBM and MI patients, but not in the lower-grade gliomas, these factors seem to be necessary for neovascularization in general, both under reactive and high-grade neoplastic conditions." (PMID 31428150, 2019).
prostate carcinoma (109 papers, 2004 to 2026). A carcinoma that arises from epithelial cells of the prostate gland. "HGF is abundantly expressed in the microenvironment of metastatic prostate cancer in the bone, and high HGF levels are often associated with metastatic PCa to bone, suggesting that HGF is a key component of regulating HGF/MET signaling in mCRPC." (PMID 40723207, 2025). "Hepatocyte growth factor (HGF) has also been linked to the enhancement of prostate carcinoma cell proliferation and invasiveness." (PMID 36899941, 2023). "In clinical studies, c-Met expression has been frequently observed in metastatic and CRPC, and higher level of HGF can be associated with poorer outcomes in prostate cancer patients." (PMID 32183146, 2020). "HGF-induced cell-cell dissociation has been linked to PAK6 activation in prostate cancer DU145 and colon cancer HT29 cells." (PMID 28475121, 2017). "This Hepsin activity is likely to be important for prostate cancer progression, because HGF/MET signaling pathway is strongly implicated in tumor progression and metastasis in prostate cancer." (PMID 24657880, 2014). "We have independently identified nucleolin protein as having a role in cancer progression, and have now linked nucleolin's function to prostate cancer cell reception of Hepatocyte Growth Factor (HGF) and integrin-based cell adhesive behaviors." (PMID 16869958, 2006). "We have identified HGF as a major signaling component of prostate stromal-conditioned media (SCM) and have implicated the protein nucleolin in HGF signal reception by the LNCaP model prostate cancer cells." (PMID 16869958, 2006). "The HGF/C-MET pathway is implicated in prostate cancer progression, and an evaluation of the inhibition of this pathway could be valuable." (PMID 28375169, 2017). "Short-term daily supplementation with Polyphenon E, a decaffeinated green tea polyphenol preparation (containing 800 mg of EGCG), in prostate cancer patients during the time between prostate biopsy and radical prostatectomy decreased cancer associated markers HGF, VEGF-A and PSA." (PMID 24039951, 2013). "Gene-expression profiling of DU145 prostate cancer cells stimulated with HGF revealed induction of a molecular signature associated with stem cells, characterized by up-regulation of CD49b, CD49f, CD44 and SOX9, and down-regulation of CD24 (‘stem-like signature’)." (PMID 22110593, 2011). "After determining that HGF is exogenously supplied to prostate cancer cells, the following experiments were performed to determine the impact of HGF/MET activity on the proliferation and phosphorylation of MET and STMN1." (PMID 40723207, 2025). "To further confirm the stromal cell expression of HGF, using 10 paired prostate cancer tissues with adjacent normal prostate tissue samples, we analyzed a single cell transcriptomic dataset of prostate cancer samples." (PMID 40723207, 2025). "In DU-145 prostate cancer (PCa) cells, HGF is reported to increase proliferation; however, STMN1 phosphorylation is not evaluated in this landmark study (439 citations)." (PMID 40723207, 2025). "After carrying out in vitro experiments, we demonstrated that ETV1 and ERG transcription factors induced migration and invasion capacities in PC3M and PC3 prostate cancer cells as well as HGF stimulation." (PMID 39374163, 2025). "Our results reveal that pelvic irradiation for prostate cancer increases the secretion of HGF, M-SCF, and MIP-1α which act synergistically to induce macrophage polarization into the M2 phenotype, possibly favoring bladder toxicity and fibrosis." (PMID 39665773, 2024). "Serum HGF levels in patients with prostate cancer were found to be significantly higher at W12 than before radiotherapy (P<.001)." (PMID 39665773, 2024). "Like HGF, the rise in IL-6 was profoundly more significant for colorectal cancer patients than breast or prostate cancer patients." (PMID 38067195, 2023). "We identified potential FOXP2-binding fragments located in MET and HGF in prostate cancer LNCaP cells." (PMID 37668356, 2023).
prostate carcinoma (continued). "Previous studies have reported that the receptor tyrosine kinase MET and its ligand HGF are important for the growth and survival of several tumor types, including prostate cancer." (PMID 37668356, 2023). "The marine natural product heteronemin exhibits potent antitumor effects by inhibiting c-Met/STAT3 activation in HGF-stimulated refractory prostate cancer cells." (PMID 35705962, 2022). "Hepatocyte growth factor (HGF) activated signaling plays a vital role in prostate cancer development." (PMID 35705962, 2022). "In search of endogenous inhibitors of TMPRSS2, Ko and coworkers performed co-immunoprecipitation assays on prostate cancer cells and identified HGF activator inhibitor (HAI)-1 and HAI-2 as interaction partners of TMPRSS2." (PMID 35163273, 2022). "For instance, the hepatocyte growth factor activates ERK/MAPK-ZEB1 signal axis to enhance the invasion ability of prostate cancer cells." (PMID 35483343, 2022). "Specific roles of HGF in the maintenance of CSCs are also reported in glioblastoma, colorectal, and prostate cancers." (PMID 34439392, 2021). "TMPRSS2 is capable of increasing the metastatic spread of prostate cancer by activating the Hepatocyte Growth Factor (HGF)." (PMID 34399734, 2021). "Judging from the protease selectivity data and potency of MM3122 and other new compounds, these are predicted to also show corresponding anticancer activity, in particular for HGF-driven prostate cancer for which TMPRSS2 is known to play a key role." (PMID 34635581, 2021). "Later, it was experimentally demonstrated that stromal cells are capable of enhancing prostate cancer cell migration and that this effect is HGF-dependent." (PMID 33535458, 2021). "Use of HC-030031, a TRPA1 inhibitor, significantly reduced the Ca2+ influx and VEGF and HGF secretion in CAFs and blocked the protective effect on prostate cancer." (PMID 34768796, 2021). "In prostate cancer cells and xenografts, the combination of increased HGF (hepatocyte growth factor) and EGF (epidermal growth factor) production, combined with the acidic extracellular pH, triggers signaling events that elevate the expression of Arl8b." (PMID 33718382, 2021). "Activation of HGF/c-Met signal can regulate prostate cancer progression and maintain cellular growth." (PMID 32183146, 2020). "We now find depletion of FASN expression increases prostate cancer cell adhesiveness, impairs HGF-mediated cell migration and reduces 3D invasion." (PMID 32139877, 2020). "In prostate cancer-associated fibroblasts, activation of TRPA1 leads to increased Ca2+ levels and elevated hepatocyte growth factor (HGF) and vascular endothelial growth factor (VEGF) secretion." (PMID 29772843, 2018). "CR in pure form can block HGF-induced signaling by specific inhibition of the c-Met/ERK/Snail pathway in prostate cancer cells." (PMID 29899871, 2018). "HGF has been shown to induce the phosphorylation of paxillin and matrix adhesion of prostate cancer cells, correlating with decreased matrix invasion." (PMID 28475121, 2017). "For example, it promotes prostate cancer cell migration in response to hepatocyte growth factor (HGF)." (PMID 28978098, 2017). "Another study also indicated the role of MT as transport mediators in the HGF-induced invasion of prostate cancer cells." (PMID 28475121, 2017). "Prostate cancer cells have shown interactions between c-Met and E-cadherin/catenin complex after HGF stimulation." (PMID 28475121, 2017). "Activation of the HGF/MET axis in prostate cancer cell lines resulted in migration and induced orthotopic tumor formation." (PMID 27105539, 2016). "Since we have previously shown that N-cadherin is the most representative marker for epithelial-mesenchymal transition in clinical prostate cancer, these findings indicate that the HGF/MET pathway plays a minor role in early hormone-naive prostate cancer." (PMID 27105539, 2016).